IGF2-AS (IGF2 antisense RNA)
Synonyms: IGF2-AS1; IGF2AS; PEG8
Gene: Long non-coding RNA gene on chromosome 11 (2,140,501 to 2,148,666, forward strand). Ensembl gene ENSG00000099869.
Diseases named in the same sentence as IGF2-AS in open-access papers:
IGF2-AS is named in the same sentence as 13 diseases in open-access papers, as found by Europe PMC text mining. Sharing a sentence is not in itself a finding about the gene and the disease. The quoted sentences say what the papers report.
melanoma (2 papers, 2019 to 2024). A malignant, usually aggressive tumor composed of atypical, neoplastic melanocytes. "In our study, IGF2as was upregulated in BRAF-mutated advanced melanoma patients compared to healthy donors, and its high expression level was linked to more favorable survival." (PMID 31231466, 2019). "In addition, circulating IGF2as was identified as an independent factor for BRAF-mutated advanced melanoma prognosis in patients receiving vemurafenib." (PMID 31231466, 2019). "Three lncRNAs are potential predictive indicators of the effectiveness of vemurafenib therapy in persons with melanoma: IGF2 antisense (IGF2AS), MEG3, along with zinc finger AE-binding homeobox 2-natural antisense transcript (Zeb2NAT)." (PMID 39777348, 2024). "We show that lncRNA IGF2AS, MEG3, and Zeb2NAT are independent prognostic factors in BRAF-mutated advanced melanoma patients treated with vemurafenib." (PMID 31231466, 2019). "When taken together, these results demonstrate that lncRNA IGF2AS, antiPeg11, MEG3, and Zeb2NAT appear to be independent prognostic factors in BRAF-mutated advanced melanoma patients treated with vemurafenib." (PMID 31231466, 2019). "Further analysis demonstrated that the baseline lncRNAs for IGF2AS, anti-Peg11, MEG3, Zeb2NAT are independent prognostic factors in BRAF-mutant advanced melanoma patients treated with vemurafenib." (PMID 31231466, 2019).
type 2 diabetes (2 papers, 2018 to 2022). "Igf2as inhibition was found to be protective in different disease models by inducing cardiac angiogenesis in type 2 diabetes and neuronal growth in neurotoxicity." (PMID 34697716, 2022). "Reciprocal regulation IGF2AS and IGF2 is critical in modulating angiogenic development in myocardial tissues in type 2 diabetes." (PMID 29867565, 2018).
breast carcinoma (1 paper, 2020). "While BC200 plays an oncogenic role in human breast cancer tissue, IGF2AS reportedly acts as an epigenetic tumor suppressor in human prostate cancer." (PMID 31319040, 2020). "Due to the 2.03-fold increase in IGF2AS in estrogen-dependent breast cancer cells after CCT137690 treatment, we hypothesized that CCT137690 may suppress invasion and metastasis in the early stages of tumorigenesis." (PMID 31319040, 2020).
diabetes (1 paper, 2022). "Notably, inhibition of IGF2AS expression was found to be protective in different disease models including local-anesthetic induced neurotoxicity and diabetes, suggesting that IGF2AS may play a detrimental role in ischemia-reperfusion injury in aged kidneys." (PMID 35627181, 2022).
infertile (1 paper, 2024). "The disappearance of the relationship between IGF2 expression and IGF2AS and H19 methylations in the infertile group provides new information regarding the disruption of epigenetic programming during spermatogenesis." (PMID 39017772, 2024). "Additionally, IGF2 mRNA expression in the fertile group was significantly correlated with IGF2AS methylation at the 2nd CpG (r = 0.388), while this correlation was not present in the infertile groups." (PMID 39017772, 2024). "However, IGF2 expression was significantly upregulated in fertile individuals whose 2nd CpG of IGF2AS was hypermethylated, unlike in the infertile group." (PMID 39017772, 2024).
lung carcinoma (1 paper, 2020). "The results of in vitro functional experiments in lung cancer cell lines suggested that high expression of IGF2AS significantly inhibited the migration of tumor cells." (PMID 31371390, 2020).
tumor (5 papers, 2020 to 2022). "Also, Igf2as was downregulated in several types of cancers and suggested to act as a tumor suppressor." (PMID 34697716, 2022). "IGF-2AS transcripts are mainly present in the cytoplasm and are associated with polysomes, suggesting that the mechanism by which IGF-2AS is involved in tumor progression may be related to the regulation of protein translation." (PMID 35963868, 2022). "Accordingly, they introduced IGF2AS as an epigenetic tumor suppressor." (PMID 31319040, 2020). "On the other hand, tumor suppressor lncRNAs (e.g., DGCR5 and IGF2AS) were upregulated in the ER-positive cell line." (PMID 31319040, 2020).
cancer (4 papers, 2018 to 2022). A tumor composed of atypical neoplastic, often pleomorphic cells that invade other tissues. "However, the function of circulating IGF2as in cancer is still unknown." (PMID 31231466, 2019).
IGF2-AS also shares sentences with these, for which no sentence is quoted: Wilms tumor (3 papers); hepatocellular carcinoma (1); Prader-Willi syndrome (1); prostate carcinoma (1); Sepsis (1).